RNU6-605P (RNA, U6 small nuclear 605, pseudogene)
Gene: Small nuclear RNA gene on chromosome 1 (38,926,870 to 38,926,977, forward strand). Ensembl gene ENSG00000199963.
Homologues: Orthologues: chimpanzee U6 (98% identical), macaque U6 (88% identical), rabbit U6 (81% identical), rat LOC120095355 (69% identical), dog U6 (64% identical). Paralogues in human: RNU6-116P (85% identical), RNU6-11P (85% identical), RNU6-37P (85% identical), RNU6-33P (84% identical), RNU6-774P (84% identical), RNU6-1 (83% identical), RNU6-1175P (83% identical), RNU6-1331P (83% identical), RNU6-15P (83% identical), RNU6-183P (83% identical), RNU6-2 (83% identical), RNU6-22P (83% identical), and 1284 more.